TLR3 (toll like receptor 3)
Diseases named in the same sentence as TLR3 in open-access papers (continued):
Sharing a sentence is not in itself a finding about the gene and the disease.
glioma (continued). "Previously, GL261 cells have also been shown to express TLR2, TLR3 and TLR4, and TLR ligands have been used as treatments against established glioma." (PMID 30974896, 2019). "It was also reported that cytokine and toll-like receptor-3 agonist (Poly-ICLC) facilitate ACT trafficking to the tumor site, thus helping to kill tumor cells and prolong the survival of glioma-bearing animals." (PMID 23667419, 2013). "Members of our research group have previously reported that combined activation of TLR3 and TLR9 may enhance the antitumor function of microglia through a synergistic effect, thereby offering a new strategy for glioma immunotherapy." (PMID 41294838, 2025). "Moreover, TLR2, TLR3, TLR4, TLR7, TLR8, and TLR9 have emerged as critical modulators of glioma biology." (PMID 41157253, 2025). "Based on the current literature, TLR3 and TLR7 agonists may be generally categorized as “safe” agonists to use in glioma therapy, as response is largely tumor inhibition in the absence of tumor promotion." (PMID 25411122, 2014). "After microglia TLR3 and TLR9 are co-activated, microglia shift to an anti-tumor phenotype and enhance migratory activity to accumulate in glioma tissue, which in turn inhibits glioma cell function by releasing cytokines or directly kills glioma cells by enhancing phagocytic activity of microglia." (PMID 37700840, 2023). "In addition, combined activation of the endosomal TLR3 and TLR9 in microglia was shown to have synergistic effect both in vitro and in vivo, reinforcing the secretion of proinflammatory factors, phagocytic activity, and suppression of glioma growth." (PMID 34715891, 2021). "Furthermore, the expression levels of PD-L1 and TLR3 were significantly higher in HCVM-IE positive-gliomas compared with HCMV-IE negative-gliomas." (PMID 33808294, 2021). "The impact of TLR3, TLR5, TLR7, TLR8, and TLR10 signaling in glioma development is not fully elucidated." (PMID 34715891, 2021). "Although engagement of TLR3 and TLR4 pathways alone, for example, may not be sufficient to eradicate tumors, targeting these receptors could be considered as a supplement to therapy until mechanisms of glioma cell suppression on microglia are more clearly understood." (PMID 25411122, 2014).
Arthritis (25 papers, 2008 to 2023). Inflammation of a joint. "However, the simulation of a viral joint infection by intra-articular poly(I:C) injections induced signs of arthritis that were also seen in TLR3-deficient (TLR3−/) mice." (PMID 35277480, 2022). "TLR3 expression was upregulated in both pristane treatment groups, especially in the pristane/poly(I:C) group, and significantly correlated with arthritis severity, suggesting that the activation of TLR3 on fibroblasts triggered by poly(I:C) causes more severe arthritis." (PMID 21708001, 2011). "TLR3 reduces HIV-1 infection and miR-26a ameliorates Pristane-induced arthritis in rats by targeting TLR3." (PMID 36685589, 2022). "miR-26a also reversely modulates TLR3 expression in murine macrophages and attenuates pristine-triggered arthritis." (PMID 31195953, 2019). "Overall, it can be concluded that the silencing of miR‐10a‐5p plays a paramount role in arthritis by regulating and promoting proinflammatory cytokines, TLR3 and MMP13 as well." (PMID 28782180, 2018). "For instance, the TLR3/TRIF agonist poly(I-C) shows beneficial effects in mouse models of arthritis, colitis, bacterial infection, and wound healing." (PMID 28465426, 2017). "In a recent study, treatment of pristane-induced arthritis rats with a miR-26a mimic decreased TLR3 expression and disease symptoms, confirming a role for TLR3 in this model." (PMID 25975607, 2015). "Our finding not only discloses the deregulation of miR-26a in TLR3 expression, but also offers a novel and reliable mechanism for abnormal TLR3 overexpression in experimental arthritis." (PMID 24423102, 2014). "Rescued miR-26a reduction and TLR3 overexpression in spleens from MTX-treated PIA rats compared with saline-treated ones also suggested the implication of miR-26a in rat arthritis." (PMID 24423102, 2014). "We demonstrate that RasGRP3, a dominant member of RasGRPs in macrophages, impairs TLR3/4/9-induced IL-6 production and relieves dextrane sulphate sodium-induced colitis and collagen-induced arthritis." (PMID 25118589, 2014). "MiR-26a mimic was administrated to PIA rats, and the results showed that TLR3 protein expression was suppressed, and the arthritis severity alleviated." (PMID 24423102, 2014). "In the pristane-induced arthritis rat model, TLR3 expression was significantly upregulated during early disease stages." (PMID 24936783, 2014). "MiR-26a negatively regulates TLR3 signaling via targeting of TLR3 itself in rat macrophages, and this finding provides a novel insight into abnormal TLR3 overexpression during experimental arthritis." (PMID 24423102, 2014). "The miR-26a mimic treatment displayed the depression of TLR3 expression and ameliorated the disease severity in the rats with pristane induced arthritis." (PMID 24423102, 2014). "Surprisingly, we have demonstrated in the present study that a compelling TLR is TLR3, which has early and stable overexpression in synovium exclusively at initiation and development stages of arthritis." (PMID 21708001, 2011). "TLR3 was expressed in FLSs, and local treatment with poly(I:C) synergistically aggravated the arthritis." (PMID 21708001, 2011). "FLSs were activated and made functional by the T cell-derived inflammatory mediator via TLR3 signaling in arthritis." (PMID 21708001, 2011). "On the basis of the ligand stimulation experiment, we concluded that overexpression of TLR3 in FLSs was involved in mediating arthritis development." (PMID 21708001, 2011). "In a previous study, intra-articular treatment with polyI:C to rats caused a rapid and strong synovitis, which suggested the important role of TLR3 signaling in arthritis pathogenesis." (PMID 20500834, 2010). "TLR3 expression increased dynamically and progressively with the arthritis initiation and development." (PMID 20500834, 2010). "We found that TLR3 positive macrophages were increased in the spleen of PIA rats, and cell surface TLR3 showed high expression in the initiation stage of arthritis." (PMID 20500834, 2010).
Arthritis (continued). "Moreover, toll-like receptors play complex roles in the pathogenesis of RA; arthritis was ameliorated when interference targeted TLR3 in rats, which suggested the important role of TLR3 in both thyroid disease and RA." (PMID 37324262, 2023). "In addition, miRNA-26a can influence the expression of Toll-like receptors in inflammatory states, as shown in a rat arthritis model for Toll-like receptor 3 protein expression." (PMID 37299658, 2023). "In addition, miR-26a ameliorates the arthritis severity of the rats through directly targeting TLR3 in rat macrophages." (PMID 35368701, 2022). "In addition, TLR3 targeted expression in rat macrophages and enhanced arthritis by inducing pristane; miR-26a negatively controlled the TLR3 signaling pathway." (PMID 33426032, 2020). "miR-26a could negatively regulate TLR3 signaling by targeting TLR3 itself in macrophages and ameliorate experimental arthritis in rats." (PMID 31275058, 2019). "In addition, it has been reported that the expression of TLR3 is increased in the spleen of rats with collagen-induced arthritis as well as in those with pritane-induced arthritis, and that the increased expression of TLR3 was decreased by treatment with MTX." (PMID 30886985, 2018). "Activation of TLR3 suppressed arthritis in the mouse CIA and K/BxN serum transfer models." (PMID 25975607, 2015). "However, TLR3 activation increased disease severity in the rat pristane-induced arthritis and rat CIA models, where upregulation of TLR3 was associated with disease and downregulation via small interfering RNA improved disease symptoms." (PMID 25975607, 2015). "Moreover, miR-26a can negatively regulate the TLR3 signalling pathway by targeting TLR3 expression in rat macrophages and ameliorates pristane induced arthritis in rats." (PMID 24772440, 2014). "MiR-26a-mimic administration also could lead to suppression of TLR3 protein expression and ameliorate arthritis in PIA rats." (PMID 24423102, 2014). "However, the direct target interaction between miRNA and TLR3 has been underestimated, and miRNA regulation of TLR3 and its signaling during arthritis development remains an enigma." (PMID 24423102, 2014). "The findings indicate that excess and persistent expression of the TLR3 gene in macrophages and synovial cells could be responsible for arthritis development." (PMID 24423102, 2014). "TLR3 was localized in FLSs, and activation of the TLR3 signaling pathway in vivo could aggravate arthritis." (PMID 21708001, 2011). "TLR3 in the synovium of PIA rats was overexpressed, and activation of the TLR3 signaling pathway could aggravate this arthritis." (PMID 21708001, 2011). "Regulating TLR3 by using ligand or shRNA in vivo could directly aggravate or relieve symptoms of arthritis." (PMID 20500834, 2010). "And in PIA rats treated with polyinosine-polycytidylic acid (polyI:C) or RNA interference (RNAi) of TLR3, arthritis manifestations could be modified." (PMID 20500834, 2010). "Furthermore, administration of polyI:C exacerbated, whereas RNA interference targeting TLR3 ameliorated, the arthritis." (PMID 20500834, 2010). "However, the cause of the upregulation of TLR3 expression and the activation of FLSs in arthritis is not known yet." (PMID 21708001, 2011). "Thus, TLR3 was confirmed to be an important mediator to bridge T cells and FLSs in arthritis." (PMID 21708001, 2011). "In summary, TLR3 in the synovium of PIA rats displayed early and persistent overexpression at the initiation and development stages of arthritis." (PMID 21708001, 2011). "The results indicated that the RNAi of TLR3 participated in the initiation of PIA significantly delayed the onset day and decreased arthritis severity." (PMID 20500834, 2010). "The data that the injection of TLR3 and TLR9 ligands into the joints induced arthritis and that TLR9 ligand CpG immunization induces arthritis in rats further support an arthritogenic role of TLRs." (PMID 18847495, 2008).
Arthritis (continued). "The induction of TLR3 in FLSs resulted from T cell-derived inflammatory stimulation and could further mediate FLS activation in arthritis." (PMID 21708001, 2011). "On the contrary, systemic TLR3 activation has been shown to suppress antibody-induced and TCR-transgenic mouse serum-induced arthritis, thus suggesting the different effect in arthritis between the local and systemic activation of TLRs." (PMID 18847495, 2008). "Although a recent study suggests that poly(I:C)-induced arthritis is regulated by the TLR3-p38 MAPK-NF-κB Il-33 pathway, which is modulated by the p65 and peroxisome proliferator-activated receptor-γ (PPARγ) complex, the role of TLR3 activation in the pathogenesis of osteoarthritis remains elusive." (PMID 35277480, 2022). "In the previous study, we found that both TLR3 mRNA and protein expressions are prominently upregulated in splenic macrophages in rats with pristine-induced arthritis (PIA) and collagen-induced arthritis (CIA), and downregulation of TLR3 expression modulates the severity of arthritis." (PMID 24423102, 2014).
colitis (23 papers, 2012 to 2025). Inflammation of the colon. "Mice pre-treated with the TLR3 agonist poly(I:C) and the TLR7 agonist, imiquimod, were protected from DSS-induced colitis, whereas mice deficient in both TLR3 and TLR7 were more susceptible to DSS-induced colitis." (PMID 37191444, 2023). "Intraperitoneal administration of TLR3 polyI:C activated MSC further reduced disease severity in mice with DSS-induced colitis through enhanced immunosuppressive activity by stimulating MSCs to increase production of indoleamine 2,3-dioxygenase (IDO)." (PMID 36356087, 2022). "Conversely, infecting mice with inactivated rotavirus prior to DSS-induced colitis protected animals from colitis, which is dependent on TLR3/7 signalling and the production of IFN-I." (PMID 35737518, 2022). "Researchers suggested that pretreatment with antiviral cocktail therapy can lead to severe colitis, and found that resident intestinal viruses played a protective role in gut inflammation through TLR3 and TLR7-mediated IFN-β secretion by pDCs." (PMID 33800865, 2021). "On the other hand, several studies have shown that TLR3 agonist poly I:C pretreatment can improve the therapeutic effect of umbilical cord mesenchymal stem cells in dextran sulphate sodium (DSS)-induced colitis." (PMID 33800865, 2021). "Another study demonstrated the protective response in colitis upon TLR-3 activation by dsRNA of lactic acid–producing commensals." (PMID 31749793, 2019). "Activation of TLR3 using poly(I:C) has been shown to ameliorate DSS colitis through maintenance of epithelial barrier integrity." (PMID 29515999, 2018). "Deletion of TLR4, TLR2, TLR5 and TLR9 as well as simultaneous deletion of TLR3 and TLR7 led to disturbed epithelial homeostasis and enhanced susceptibility to acute DSS-induced colitis, however with less severe pathology than in MyD88-deficient mice." (PMID 29570694, 2018). "Commensal bacteria triggered the production of IFN-β via recognition of dsRNA by TLR3, which in turn protected mice from experimental colitis." (PMID 28428788, 2017). "Additionally, polyinosinic-polycytidylic acid (poly-I:C, TLR3 agonist) treatment was shown to protect mice from tissue damage in DSS colitis in a TLR3-dependant manner." (PMID 34712246, 2021). "Indeed, TLR3 has already been observed to protect mice from colitis due to its ability to sense dsRNA produced by commensal lactic acid bacteria and suppress inflammatory responses reserved for pathogenic bacteria." (PMID 31952471, 2020). "ICMT and RAS expressions were strongly increased in macrophages under the activation conditions of TLRs by lipopolysaccharide (LPS, a TLR4 ligand), pam3CSK (TLR2), or poly(I:C) (TLR3) and in the colons, stomachs, and livers of mice with colitis, gastritis, and hepatitis." (PMID 32422978, 2020). "Similarly, administration of individual synthetic ligands for TLR3, TLR7 and TLR9 had protective effects against colitis in mice, which were also associated with the induction of type I IFNs." (PMID 29570694, 2018). "In addition, a study demonstrated that stimulation of TLR-3 on macrophages with dsRNA could lessen the symptoms of DSS-induced colitis." (PMID 31749793, 2019). "The increased susceptibility to DSS-induced colitis in mice lacking TLR3 and 7, which primarily sense viruses, may indicate that sensing of resident enteric viruses by these receptors protects the epithelium from colitis." (PMID 29570694, 2018). "In that study it was also shown that the oral application of combined TLR3 and TLR7 agonists or inactivated rotavirus particles protected mice against DSS-induced colitis." (PMID 29570694, 2018). "When administered as a preventive measure, ligands for TLR9 (CpG) or TLR3 (polyI:C) also induced IFN-I and lessened disease severity of DSS-induced colitis." (PMID 28428788, 2017).
colitis (continued). "TLRs in non-immune cells have been implicated in multiple autoimmune and inflammatory diseases, including Hashimoto’s thyroiditis (TLR3 in thyrocytes), colitis (TLR4 in intestinal epithelial cells and type 1 diabetes (TLR3 in pancreatic ß-cells)." (PMID 22685570, 2012). "TLR3 signals the presence of virus-derived double stranded RNA, but mRNA released from damaged or necrotic epithelial cells can also lead to TLR3 activation, which has been shown to protect against DSS-induced colitis." (PMID 23062310, 2012). "Consequently, we aimed in the study at hand to assess whether administering TLR3, 7, or 9 inhibitors alleviates EBV DNA-exacerbated colitis and whether combining these inhibitors has a relevant additive effect on colitis amelioration." (PMID 38675965, 2024). "The effect of TLR3, 7, and 9 inhibition on the DAI in the EBV DNA-exacerbated IBD mouse model was determined on a daily basis by collecting data pertaining to body weight, fecal consistency, and occult blood, and trends were observed to evaluate the severity of colitis." (PMID 38675965, 2024). "Furthermore, in a mouse model of induced colitis, intraperitoneal but not intravenous injection of TLR3 activated MSC was found to attenuate disease severity." (PMID 36356087, 2022). "Lack of TLR3 and TLR7 during DSS colitis abrogated IFN-β production of colonic pDCs in response to TLR3/7 agonists indicating that type I IFN produced by pDCs may be important to counterregulate inflammation in the colon." (PMID 29570694, 2018).